BCL2 (BCL2 apoptosis regulator)
Diseases named in the same sentence as BCL2 in open-access papers (continued):
Sharing a sentence is not in itself a finding about the gene and the disease.
cancer (continued). "Bcl-2 levels are normally up-regulated in cancer cells as a means to safeguard them from apoptosis induction; this protein is also downstream of caspase-8." (PMID 21234313, 2011). "In this study, we demonstrate that Bcl2 and caspase 8 interact in cancer cells that have become refractory to therapy, thus providing another mechanism by which Bcl2 promotes survival and drug resistance." (PMID 22069448, 2011). "An intracellular anti-Bcl-2 single chain antibody has been shown to increase drug-induced cytotoxicity in the MCF-7 breast cancer cell line as well as other cancers." (PMID 21760983, 2011). "It has been suggested that the Bcl-2 signaling pathway of apoptosis plays an important role in the killing of targeted cancer cells by immunotoxins." (PMID 21305058, 2011). "In a number of cancer cell lines, miR-16 has been shown to be involved in the induction of apoptosis by targeting BCL-2 and in cell cycle regulation by targeting CDK6, CDC27, and CARD10." (PMID 21698265, 2011). "These novel interactions between Bcl2 and other proteins, as demonstrated by us and others, highlight the complex mechanisms utilized by cancer cells to evade cell death, leading to disease progression and drug resistance." (PMID 22069448, 2011). "Cancer cells have deregulated apoptotic pathways, where increased expression and stability of anti-apoptotic proteins Mcl-1 and Bcl-2 increases resistance to apoptosis." (PMID 21730980, 2011). "Taken together, these results suggest that survivin down-regulation plays a critical role for anti-cancer drug Bcl-2 inhibitor to induce apoptosis in HCC cells." (PMID 21829603, 2011). "In this study, we show that two dynamin inhibitors called the MiTMABs induce cytokinesis failure and induce apoptosis in cancer cells and this appears to correlate with low expression of the anti-apoptotic proteins Bcl-2 and Mcl-1." (PMID 21708043, 2011). "Compared with TG2-knocked-down cells (shTG2_MB231#1), control cancer cells (cont_MB231) cultured in sphere medium expressed more antiapoptotic molecules, such as cIAP2 and Bcl-2." (PMID 21967801, 2011). "Considered initially as oncogenes, the prognostic impact of BCL-2/MCL-1 for various type of cancer is debated due to their dual function on cell death and cell proliferation." (PMID 21401964, 2011). "Bcl-2, an upstream effector molecule in the apoptotic pathway, has been recognized to be a potent suppressor of apoptosis, and most cancers generally overexpress Bcl-2." (PMID 21660305, 2011). "Accordingly, knockdown of intracellular S1P lyase in cancer cells was shown to disrupt apoptosis and results in chemoresistance by Bcl-2/Bcl-xL upregulation." (PMID 21829623, 2011). "This structure is a promising target for cancer therapy because it regulates the crucial process of proteasome-mediated protein degradation, which involves many proteins such as cyclins, caspases, Bcl-2 and the nuclear factor of κB (NF-κB)." (PMID 22078414, 2011). "Persistent nicotine exposure was shown to upregulate Bcl-2, which enhances cell survival as well as resistance of cancer cells to chemo-drugs." (PMID 22085699, 2011). "As an extension to these earlier observations, the current study demonstrates that in cancer cells that have become resistant to chemotherapy, the N-terminus of caspase 8 interacts instead with Bcl2 to restrict apoptosis." (PMID 22069448, 2011). "Bcl-2 was strongly expressed mainly in the cytoplasm and membranes of cancer cells, with 51.4% higher scores (19 of 37)." (PMID 21034499, 2010). "Bcl-2 also mediates the resistance of cancers to conventional therapies such as radio- and chemo-therapy." (PMID 20184758, 2010).
cancer (continued). "In HPV-positive cancers Bcl-2 overexpression and Bax degradation by E6 facilitates cancer progression." (PMID 20673369, 2010). "Previously, we have generated Bcl-2, Bcl-X(L) and survivin specific cytotoxic T cell clones and examined the killing of a panel of cancer cell lines." (PMID 21304176, 2010). "In cancer cells, Bcl-2 inhibits over-expressed BH3 molecule such as Bid, which can directly activate Bax with a very small rate constant, and thus through the Bid-Bcl-2-Bax loop stochastic Bax activation is generated." (PMID 20711445, 2010). "While co-expression of Bcl-2 and Bcl-X(L) is seen in some cancers, others exhibit exclusive expression of one or the other protein." (PMID 21304176, 2010). "It has been reported that miR-181b modulates multidrug resistance in human cancer cell lines by targeting Bcl-2, a protein that has an important anti-apoptotic role." (PMID 23554660, 2010). "The SROs in these chromosome arms contains a number of protein coding genes, including well known critical cancer genes as BCL2 (18q22), DCC (18q21) and AURKA (20q13)." (PMID 20459617, 2010). "For very high Bcl-2 levels, as observed in some cancer cells, apoptotic activation is strongly inhibited with rare stochastic activations of a few cells." (PMID 20711445, 2010). "Bcl-2 and Mcl-1 are often highly expressed in chemotherapy-resistant cancers and prevents apoptosis by inactivating pro-apoptotic Bax and Bak." (PMID 20663232, 2010). "As main members of Bcl-2 family, the antiapoptotic gene Bcl-2 and proapoptotic gene Bax were analyzed in most human cancers which played important roles in tumorigenesis and development." (PMID 20698986, 2010). "On the opposite side, high Bcl-2 expression also correlated with favorable parameters and a better prognosis in other cancers." (PMID 20403207, 2010). "Some members of the Bcl-2 family of proteins, such as Bcl-2 and Bcl-xL, also play a role in apoptosis and have been found to be elevated in different types of cancer cells." (PMID 22069560, 2010). "These triterpenoids have a common target, the antiapoptotic protein Bcl-2, which can induce apoptosis in cancer cells." (PMID 22069560, 2010). "In general, over-expression and up-regulation of Bcl-2 has been associated with resistance to chemotherapy in various human cancers, and many studies have shown that over-expression of Bcl-2 is a poor prognostic factor in various cancers." (PMID 20403207, 2010). "In many human cancers, the anti-apoptotic Bcl-2 proteins are over expressed, or the pro-apoptotic proteins, like Bax, have reduced expression." (PMID 20441573, 2010). "Using immunohistochemistry, the expressions of CK7, CK19, CK20, GCDFP-15, CEA, S-100 protein and bcl-2 were examined to elucidate the cellular differentiation of the carcinoma." (PMID 20684770, 2010). "CXCL12 producing carcinomas cultured on poly-HEMA displayed heightened Bim and loss of Mcl-1 and Bcl-2 preceding cytochrome c release, and caspase-9 activation." (PMID 20877573, 2010). "Contrary to other cancers, the well-known anti-apoptotic BCL2, the FOS oncogene and the multidrug resistance gene ABCB1 (ATP-binding cassette sub-family B member 1) were down-regulated." (PMID 19662092, 2009). "BAG-1, BCL-2 and ER feature among the 16 cancer-related genes of the Oncotype Dx assay, which predicts distant failure in ER+ lymph node-negative patients treated with tamoxifen." (PMID 19066611, 2009). "The survival protein Bcl-2 is upregulated in many cancer cells, and several current antileukemic drugs like daunorubicin fail to kill Bcl-2 overexpressing cells." (PMID 20098602, 2009). "This is in agreement with other studies which reported greater Bcl-2 expression in normal and benign specimen compared to cancer samples." (PMID 19852858, 2009).
cancer (continued). "Among the target proteins regulated by miR-34 are Notch pathway proteins and Bcl-2, suggesting the possibility of a role for miR-34 in the maintenance and survival of cancer stem cells." (PMID 19714243, 2009). "Further, epithelial Bcl-2 staining was greater in normal and benign ovarian specimens compared with cancer specimens." (PMID 19852858, 2009). "The interaction of Bcl-xL with Bax prevents Bax induced cell death, where drugs that disrupt Bcl-xL interacting with Bcl-2 proteins are a promising form of cancer therapy." (PMID 19823588, 2009). "Epithelial Bcl-2 staining was present in 91% (10/11) normal, 100% (17/17) benign, and 79% (22/28) cancer specimens." (PMID 19852858, 2009). "Similar to what was reported for Bcl-2, cancer cells exposed to low doses of radiation up-regulated COX-2 expression as a possible means to survive the radiation exposure." (PMID 19589167, 2009). "We transduced cancer cells to overexpress crmA which inhibits initiator caspases including caspase-1 and caspase-8 in the death-receptor pathway, or Bcl-2, a well-known inhibitor of multiple caspases in the mitochondrial pathway." (PMID 19247489, 2009). "As the next section will illustrate, Bcl-2 expression can result in the development of radiation-resistant cancers." (PMID 19589167, 2009). "Anti-mRNA drugs targeted at the antiapoptotic Bcl-2 protein emerged as undisputed leaders among the gene-targeted oligonucleotides used for cancer treatment." (PMID 22649602, 2009). "Overexpression of bcl-2 has been reported in a wide variety of cancers including prostate, colorectal, lung, renal, bladder and leukemia." (PMID 19243595, 2009). "This is of interest since an important challenge in cancer therapy is to overcome treatment resistance due to cancer cell overexpression of survival proteins like Bcl-2." (PMID 20098602, 2009). "It has been reported that miR-34 targets Notch, c-Met and Bcl-2, genes involved in the self-renewal and survival of cancer stem cells." (PMID 19714243, 2009). "Along with the growing experimental evidences, our studies successfully elucidate the switch mechanism embedded in the Bcl-2 interaction network and provide insights into pharmacological manipulation of Bcl-2 apoptotic switch as further cancer therapies." (PMID 18213378, 2008). "It has been reported that miR-34 targets Notch, HMGA2, and Bcl-2, genes involved in the self-renewal and survival of cancer stem cells." (PMID 18803879, 2008). "The ERK1/2 pathway is activated in many types of cancer and it promotes cell survival, i.e. it induces anti-apoptotic genes such as Bcl-2 and inactivates the pro-apoptotic Bad." (PMID 18822184, 2008). "miR-34 targets Notch, HMGA2, and Bcl-2, genes involved in the self-renewal and survival of cancer stem cells." (PMID 18803879, 2008). "Bcl-2 has been shown to inhibit chemotherapy-induced apoptosis, and chemotherapy resistance has been reversed in cancer cells treated with Bcl-2-targeting therapy." (PMID 18430249, 2008). "Other miRNAs, such as miR-15 and miR-16, have been reported to be able to downregulate Bcl-2, a proto-oncogene overexpressed in many type of cancers, leading to a prevention of apoptosis." (PMID 18803879, 2008). "In this study, normal patients were younger (≤ 40 years of age) than cancer patients (> 41 years of age) and based on Allred scoring, all tissue samples were positive for Bcl-2 staining (score = 3)." (PMID 18652667, 2008). "Bcl-2 is a key inhibitor of apoptosis and protects cancer cells from apoptosis induced by chemotherapeutic agents." (PMID 18803879, 2008). "With regard to suppression of Bcl-2 by COX-2 inhibitors, some previous studies have shown that the ability of COX-2 inhibitors to induce apoptosis in cancer cells depends on the downregulation of Bcl-2." (PMID 17612393, 2007).
cancer (continued). "Immunoprecipitation of 14-3-3ζ protein revealed its binding to p65 subunit of NFκB, β-catenin and Bcl-2 proteins suggestive of its involvement in inflammation, survival and proliferation of cancer cells." (PMID 17764575, 2007). "The prevalence of survival over proliferation was confirmed by Bcl-2 or Bcl-XL increase in cancer versus mucosa, and by decreased PPARα." (PMID 17389773, 2007). "The bcl-2 gene was initially identified in human B-cell lymphoma because of its activity as an inhibitor of apoptosis in cancer cells." (PMID 17430582, 2007). "The shorter survival of patients with ABC DLBCL is connected to pathways expressed differently from GCB DLBCL; thus the well known BCL2, as a central apoptosis blocker is higher expressed and allows cancer cell survival in ABC DLBCL." (PMID 19455257, 2007). "Elucidation of the precise mechanism by which COX-2 inhibitors downregulate Bcl-2 will help to clarify the appropriate uses of COX-2 inhibitors in preclinical settings for treating cancer." (PMID 17612393, 2007). "As a consequence, the expression of bcl-2 in cancer cells is thought to inhibit apoptosis and therefore relate to a worse outcome." (PMID 17430582, 2007). "Previous studies of apoptosis in OSCC have described a correlation between high AI and well-differentiated carcinomas and between the antiapoptotic protein Bcl-2 and high histological grade (less differentiated carcinomas)." (PMID 17437012, 2007). "Here we observed down-regulation of BCL2 and its neighbors which is contradictory to its known anti-apoptotic cancer-promoting function." (PMID 16982006, 2006). "The prognostic significance of Bcl-2 and p27 protein expressions has been well demonstrated in various cancers." (PMID 16839413, 2006). "Bcl-2 and Bcl-XL are anti-apoptotic paralogues that inhibit apoptosis elicited by a wide variety of stimuli, and play critical roles in cancer development and resistance to treatment." (PMID 16928273, 2006). "FV treatment was also found to down regulate the expression of Bcl-2 when compared to cancer control." (PMID 17137521, 2006). "Although the role of bcl-2 protein is well known in some forms of low grade lymphomas, including follicular lymphomas, its role in other cancers is under investigation." (PMID 16759362, 2006). "Its special role in cancer qualified the anti-apoptotic BCL2 protein as a therapeutic target molecule." (PMID 16982006, 2006). "Bcl-2-positive cancers presented with lower PI determined with Ki-67 (P=0.039), which can explain the better prognosis in non-metastatic cases reported previously." (PMID 17031406, 2006). "In many cancers, the anti-apoptotic protein Bcl-XL and Bcl-2 are found to be over-expressed while the activity of pro-apoptotic Bax is counterbalanced by strong surviving signals." (PMID 15907209, 2005). "High levels of Bcl2 protein expression have been found in many different types of cancer, suggesting a possible role for Bcl2 deregulation of apoptosis and malignant tissue transformation." (PMID 15357873, 2004). "High levels of Bcl-2 protein expression have been found in many different types of cancer, suggesting a possible role for Bcl-2 to deregulate apoptosis and promote malignant tissue transformation." (PMID 14710230, 2004). "We show that the expression of Bax and Bcl-2 controls the sensitivity of the cancer cells toward the immune system." (PMID 15331018, 2004). "The effect of modifying single members of the BCL-2 gene family on apoptotic response has been examined in a variety of cancer types and models." (PMID 12865934, 2003).
cancer (continued). "Taxanes induce synchronization of cancer cells to the radiosensitive G2/M phase of the cell cycle and, furthermore, induce phosphorylation of the anti-apoptotic bcl-2 protein, which enhances radiation apoptosis." (PMID 12177774, 2002). "In addition to its role in cell cycle regulation, miR-15a-5p has been widely recognized for its ability to modulate apoptosis through direct targeting of BCL2, a key anti-apoptotic protein that promotes cancer cell survival." (PMID 41561226, 2026). "Moreover, the second- and third-generation models shared co-targetable dysregulations in cancer stemness regulators (Hedgehog, Notch), anti-apoptotic protein BCL-2, and the drug efflux transporter ABCG2." (PMID 42087187, 2026). "This study provides the first evidence that pharmacological concentrations of VC induce the expression of pro-apoptotic proteins such as Apaf-1 and caspases -7 and -9, while inhibiting cancer cell survival proteins like Bcl-2, cyclins D and B1, CDK2, Akt, pI3K, and mTOR." (PMID 40149617, 2025). "Yet, further work is needed to assess its effect in other BCL2-dependent cancer types." (PMID 40113751, 2025). "Furthermore, gene expression analyses revealed significant upregulation of caspase 9 and key alterations in cancer‐related genes, including Bcl‐2, Bax, and GAPDH, implicating the caspase 9‐mediated apoptotic pathway as a central mechanism of action." (PMID 40079412, 2025). "Additionally, 5-FU can induce apoptosis through mechanisms involving the modulation of the Bax/Bcl-2 or Bcl-xl ratio, further enhancing its cytotoxic effects against cancer cells." (PMID 40243608, 2025). "Additionally, BCL-2, which is also present in the antioxidant target intersection, plays a crucial role in regulating apoptosis and oxidative stress in cancer cells." (PMID 40363725, 2025). "Moreover, the study showed an increase in apoptotic markers such as Bax/Bcl-2 and caspases 3 and 9, further enhancing the apoptotic response in cancer cells." (PMID 39861761, 2025). "Collectively, these results support a model in which ATP5IF1 overexpression compromises AML cell viability in response to stress, highlighting matrix ATP consumption as a cancer cell–specific bioenergetic vulnerability, particularly relevant in the context of BCL-2-targeted chemotherapy." (PMID 40203117, 2025). "Anti-apoptotic proteins, including Bcl-2, are frequently found to be overexpressed in cancer cells." (PMID 41009501, 2025). "Similarly, overexpression of anti-apoptotic proteins such as Bcl-2 and Bcl-XL, often due to chromosomal translocations, contributes to cancer development and treatment resistance." (PMID 41472305, 2025). "Natural fucoidans induce apoptosis in various cancer cells through both the intrinsic mitochondrial pathway and the extrinsic death receptor pathway, often involving the activation of caspases, altered Bcl-2/Bax ratios, and the modulation of MAPK/ERK and PI3K/AKT signaling pathways." (PMID 41009793, 2025). "Venetoclax has shown significant efficacy in both AML and ALL, while dasatinib (inhibiting BCR:: ABL1) and vinaclotide (inhibiting BCL-2) have a strong synergistic effect, which may effectively “starve” and “kill” cancer cells." (PMID 41366999, 2025). "Furthermore, the development of peptides that modulate apoptotic pathways, particularly those that target anti-apoptotic proteins like Bcl-2 and Bcl-XL, has shown promise in reversing apoptosis evasion, a key mechanism of resistance in Tx-treated cancer cells." (PMID 41114937, 2025).